PDPK2P (3-phosphoinositide dependent protein kinase 2, pseudogene)
Description:
Phosphorylates and activates not only PKB/AKT, but also PKA, PKC-zeta, RPS6KA1 and RPS6KB1. May play a general role in signaling processes and in development (By similarity).
Gene: Transcribed unprocessed pseudogene on chromosome 16 (2,616,453 to 2,642,432, reverse strand). Ensembl gene ENSG00000205918.
Subcellular location: Cytoplasm; Membrane
Diseases named in the same sentence as PDPK2P in open-access papers:
PDPK2P is named in the same sentence as 3 diseases in open-access papers, as found by Europe PMC text mining. Sharing a sentence is not in itself a finding about the gene and the disease. The quoted sentences say what the papers report.
hepatocellular carcinoma (5 papers, 2022 to 2025). A malignant tumor that arises from hepatocytes. "According to research, LncRNA-PDPK2P promotes hepatocellular carcinoma (HCC) progression via the PDK1/Akt/Casepase-3 signaling pathway, and PDPK2P expression can be used as a prognostic marker for HCC." (PMID 37064115, 2023). "LncRNA PDPK2P promotes AKT phosphorylation and inhibits the expression of caspase-3 by interacting with PDK1, and then inhibits the apoptotic pathway of hepatocellular carcinoma cells and promotes proliferation of tumor cells." (PMID 37313458, 2023).
liver cancer (1 paper, 2023). An epithelial or non-epithelial malignant neoplasm that arises from the liver. "For example, lncRNA PDPK2p/PDK1/AKT/caspase-3 signaling pathway can inhibit apoptosis, while the lncRNA MAGI2-AS3/miR-374b-5p/Smg1 axis can promote apoptosis in liver cancer cells." (PMID 37313458, 2023).
tumor (3 papers, 2021 to 2022). "Studies have indicated that the lncRNAs, MIAT, GABPB1, and PDPK2P influence tumor progression in HCC." (PMID 34876904, 2021).